AR (androgen receptor)
Diseases named in the same sentence as AR in open-access papers (continued):
Sharing a sentence is not in itself a finding about the gene and the disease.
polycystic ovary syndrome (54 papers, 2010 to 2026). A disorder that manifests as multiple cysts on the ovaries. "The association between AR gene polymorphism and polycystic ovary syndrome will be discussed later (in the AR section)." (PMID 38152131, 2023). "Arsenic has been shown to regulate steroid receptors such as the androgen receptor, which has been linked to ovarian dysfunction, manifested by the development of polycystic ovaries." (PMID 23526987, 2013). "Androgens, via binding to the androgen receptor encoded by the Nr3c4 gene, are essential for maintaining ovarian function, i.e., follicular growth and estrogen synthesis, and they are also implicated in ovarian disease such as polycystic ovarian syndrome." (PMID 40141115, 2025). "Gene factors such as polymorphisms in androgen receptor gene and follistatin gene might contribute to hyperandrogenemia in women of PCOS, while genetic change in melatonin receptor 1B gene may impair insulin secretion and increase FPG." (PMID 34248844, 2021). "However, hyperandrogenemia is also associated with β-cell dysfunction and type 2 diabetes raising the possibility that androgen receptor (AR) activation predisposes to β-cell failure." (PMID 20585581, 2010). "In granulosa cells, the androgen receptor insertion and deletion isoforms of AS variants disrupted follicle growth and androgen metabolism, resulting in polycystic ovary syndrome (PCOS), which is a common disease that results in infertility." (PMID 37248466, 2023). "The effects of pharmacological androgen reduction or androgen receptor antagonists on insulin sensitivity have been less consistent; however, Mendelian randomization in a population-based study has supported a causal link between hyperandrogenemia and both PCOS and type 2 diabetes." (PMID 33901270, 2021). "Persistent androgen receptor (AR) activation is an important contributor to polycystic ovary syndrome (PCOS) and is affected by transcriptional regulation via histone acetylation; however, the underlying mechanisms are partially understood." (PMID 41684293, 2026). "AR activation induces FTO upregulation, and the interaction of upregulated FTO promotes the expression of the AR signaling pathway and steroid synthase with AR, creating a positive feedback mechanism that promotes hyperandrogenemia in PCOS." (PMID 40410881, 2025). "In granulosa cells from women with polycystic ovarian syndrome, unique AR-SVs lead to an increase in androgen production." (PMID 37626712, 2023). "Although chronic androgen exposure in female mice models the metabolic and reproductive impairments of polycystic ovary syndrome and up‐regulates androgen receptor expression in the hypothalamus, luteinizing hormone pulsatility is not elevated." (PMID 35267218, 2022). "In two in vivo experiments, QUR inhibits androgen receptor expression in the ovaries of rats with polycystic ovary syndrome induced by dehydroepiandrosterone (DHEA)." (PMID 35889348, 2022). "Research in polycystic follicular syndrome has found that neuroendocrine androgen action is a key extra ovarian mediator in the development of polycystic ovary syndrome, and the role of extra ovarian AR in follicle development cannot be ignored." (PMID 35046998, 2021). "In fact, AR rs6152 has been related to polycystic ovary syndrome, which in turn have been related to higher levels of neuroticism." (PMID 33690629, 2021). "Overexpression of AR was observed in the granulosa cells, luminal, and glandular epithelium of endometrium in polycystic ovaries compared to normal ovaries." (PMID 30944702, 2019). "Second, hyperandrogenemia can induce a low-grade inflammatory state by increasing the transcripts of the androgen receptor and the release of TNF-α from mononuclear cells, and both contributes to the development of NAFLD." (PMID 29747678, 2018).
polycystic ovary syndrome (continued). "Considerable evidence from human and animal studies currently reinforces the hypothesis that androgens in excess, working via the AR, play a key role in the origins of polycystic ovary syndrome (PCOS)." (PMID 31466345, 2019). "Notoriously, mutations in the genes of the androgen receptor, sex hormone binding globulin (SHBG), and steroidogenic enzymes may be especially important in predisposing to the development of hyperandrogenemia." (PMID 25763405, 2014). "Indeed, AR-blocker therapy by itself ameliorated several metabolic functions and, when used as cotreatment, prevented several dysfunctions induced by hyperandrogenemia." (PMID 24066237, 2013). "Hyperandrogenemia induced by DHT is characterized by down-regulation of granulosa cell AR in rat preantral which could be restored by FSH administration." (PMID 23675970, 2013). "The extent to which the AR plays a role in systemic oxidative stress and β-cell failure in female rodents with hyperandrogenemia is unknown." (PMID 20585581, 2010). "Because high testosterone and LH levels are hallmarks of polycystic ovary syndrome (PCOS), we assessed if AR in LepR neurons plays a role in the neuroendocrine dysregulation of hyperandrogenemia-induced PCOS-like phenotype in mice." (PMID 40276575, 2025). "Our data significantly indicate that the liver AR does not play a critical role in the reproductive dysfunction associated with hyperandrogenemia in lean conditions, and that hyperandrogenemia affects reproductive function even in the absence hepatic associated metabolic derangements." (PMID 35757434, 2022). "While excess androgen level leads to polycystic ovary syndrome (PCOS), a certain amount of direct androgen actions through the androgen receptor (AR) are essential for normal ovarian function." (PMID 33784295, 2021). "11-hydroxy and 11-ketoandrogens have been shown to activate the androgen receptor to a greater extent as opposed to classical androgens and to be associated to a number of pathological conditions such as the polycystic ovary syndrome." (PMID 33675863, 2021). "The results confirmed the effect of EA on adjusting hormone levels and polycystic ovary morphology in PCOS rats as well as regulating ovarian local factors such as AMH, INHB, AR, or Cx43." (PMID 32733580, 2020). "Following our novel observation of nail changes with the hyperandrogenemia in a post menopausal SLCT patient, we evaluated the presence of androgen receptors (AR) in the nail bed of normal healthy women." (PMID 25296983, 2014). "It is possible that the negative obesogenic effects of long-term hyperandrogenemia on total body fat mass are mitigated in part by the positive AR thermogenic action in BAT." (PMID 38987854, 2024). "Although chronic hyperandrogenism suppresses antral follicular development, a phenomenon often observed in polycystic ovarian syndrome (PCOS), whether and how deregulation of androgen receptor (AR) signaling is involved, is not well understood." (PMID 28860512, 2017). "Polycystic ovary syndrome (PCOS) is a common gynaecological disorder, with a prevalence of up to 12% of women of reproductive age, and is in part characterised by elevated circulating androgens and aberrant expression of androgen receptor (AR) in the endometrium." (PMID 31256208, 2019). "Our results showed the M-CAG allele had the highest risk (about 3-fold to S-CAG alleles and 1.3-fold to L-CAG alleles) for ALF, which is concordant with the non-linear association between AR CAG repeat length and risk of subfertility or polycystic ovary syndrome." (PMID 24391916, 2013).
endometrial cancer (52 papers, 2008 to 2026). Primary or metastatic malignant neoplasm involving the endometrium (mucous membrane that lines the endometrial cavity). "AR expression is also found in a large majority of endometrial cancers and is associated with a good prognosis." (PMID 29642629, 2018). "The androgen receptor (AR) poly‐glutamine polymorphism (AR‐Q) was reported to play role in endometrial cancer (EMCA) development, yet controversial." (PMID 28782227, 2018). "Epidemiological evidence suggests that elevated androgen levels and genetic variation related to the androgen receptor (AR) increase the risk of endometrial cancer (EC)." (PMID 26397136, 2015). "Finally, as PCOS patients have an increased risk of developing endometrial cancer (EC), we considered whether any AR targets were implicated in this disease." (PMID 31256208, 2019). "A previous study demonstrated that a significant proportion of metastatic endometrial cancers express AR." (PMID 41486951, 2026). "Overall, our findings are similar to the results of recent studies of AR expression in endometrial cancers." (PMID 40392873, 2025). "Previous reports have described only point mutations of the gene encoding the AR in POI patients, while short poly-Q polymorphisms have been associated with poorer prognosis only in endometrial cancer." (PMID 41458559, 2025). "The progression and therapy of various cancers, including breast and endometrial cancer, are significantly influenced by the presence of AR, ER alpha, and PR." (PMID 38523927, 2024). "Selective androgen receptor modulators (SARMs) have rekindled interest in targeting receptors for endometrial disorders, such as endometriosis, adenomyosis, or endometrial cancer, due to their antiproliferative effects." (PMID 38543097, 2024). "AR staining was unrelated to histopathological features and clinical features in 157 endometroid endometrial carcinomas and in 221 serous ovarian carcinomas." (PMID 38790919, 2024). "Our findings show that androgen receptor is strongly expressed, more so than ER and PR, in most endometrial cancers, notably in the high-grade malignancies." (PMID 37725629, 2023). "The expression of AR in postmenopausal endometrium is significantly higher compared to the proliferative endometrium, and the expression of AR is significantly higher in metastatic endometrial cancer compared with primary tumours." (PMID 37872211, 2023). "In this series, we evaluated the expression of AR and its comparison to ER and PR in different types of endometrial cancers and have reviewed the literature." (PMID 37725629, 2023). "This drug prevents the nuclear translocation of AR and its sequence-specific binding to DNA, resulting in cellular apoptosis in endometrial cancers." (PMID 37725629, 2023). "There have been suggestions that androgen receptor expression in endometrial cancer can also contribute to the prognosis." (PMID 36836575, 2023). "The aim of this review is to discuss the role of androgens in the progression of endometrial carcinoma (EC) with particular focus on the different kinds of androgenic hormones, androgen receptor (AR) and intracrine androgen metabolism." (PMID 36583833, 2023). "It has been reported that MFE-296 endometrial cancer cells express AR in vitro, and both progestin and DHT treatment can inhibit the proliferation of MFE-296 cells." (PMID 36358974, 2022). "The role of androgen receptor (AR) in evaluating the prognosis of patients with endometrial cancer (EC) remains controversial." (PMID 35814433, 2022). "Recent data imply that AR positivity is seen in a subset of endometrial carcinomas and is expressed conversely to ERs." (PMID 35372016, 2022). "The interaction of androgen, estrogen and progesterone hormones with specific receptors (AR, ER, PR) has emerged as a key player in the development and progression of breast, ovarian, prostate and endometrium cancers." (PMID 33552000, 2020).
endometrial cancer (continued). "Our data are consistent with other studies performed in EOC breast and endometrial cancer that suggest a positive prognostic role of AR expression." (PMID 32366278, 2020). "On the other hand, AR was required for FOXA1-enhanced Notch pathway activation in endometrial cancer cells, increasing Notch1 and HES1 expression." (PMID 33167316, 2020). "Genome-wide AR analysis in PCOS stromal cells revealed that AR targets included genes involved in cell death and apoptosis, as well as genes commonly dysregulated in endometrial cancer." (PMID 31256208, 2019). "Our own previous work showed that the interaction of AR/AhR promoted endometrial cancer progression under AhR ligand (TCDD) treatment." (PMID 30986993, 2019). "We found that a significant subset of endometrial cancers express androgen receptor especially a serous cancers; therefore we suggest that androgen receptor expression testing should be done in endometrial carcinoma." (PMID 29747687, 2018). "The importance of androgens as etiological factors has been supported also by the expression of the androgen receptor and the presence of androgen-metabolizing enzymes in well and moderately differentiated endometrial cancer." (PMID 28674494, 2017). "Androgen receptor (AR) is a hormone receptor less studied in endometrial cancer, although a target for treatment in other cancers." (PMID 27384477, 2016). "As there are several available treatments targeting AR, further studies should be conducted to investigate their potential in treatment of endometrial cancer." (PMID 27384477, 2016). "Endometrial cancer epithelial AR correlated positively with PR (r=0.63, P<0.0001), whilst there was a negative correlation with Ki67 (r=−0.43, P= 0.0004)." (PMID 26930451, 2016). "Endometrial cancer (EC) is a hormone-driven disease, and androgen receptor (AR) expression in high-grade EC (HGEC) and metastatic EC has not yet been described." (PMID 26930451, 2016). "Androgen receptor (AR) is a hormone receptor less studied in female cancers, and we here aim to investigate the expression level of AR in endometrial cancer precursor lesions, primary tumors and metastases, and its potential as therapeutic target." (PMID 27384477, 2016). "In this study we show that also AR is a prognostic marker in endometrial cancer as earlier well documented for ERα and PR." (PMID 27384477, 2016). "Here, we show that testosterone stimulates the activation of both ERK1/2 and the Akt signaling pathways in endometrial cancer Hec1A cells that lack expression of ER-α66 and AR." (PMID 19775474, 2009). "In summary, AR is found to be expressed in a high percentage of most ovarian malignancies with higher rates of positivity and stronger intensity than ER and PR, similar to the study on endometrial cancers." (PMID 40392873, 2025). "The mechanism for this may be via displacement of oestrogen-regulated transcription factors by the androgen receptor, reducing oestrogen-driven cell cycle activation and thus inhibit endometrial cancer growth." (PMID 40687741, 2025). "Also, in their study, 39% of the metastatic endometrial cancers have shown a higher rate of AR expression than ER." (PMID 37725629, 2023). "AR is expressed in a high percentage of endometrial cancers." (PMID 37725629, 2023). "While hormonal therapy targeting ER and PR is used in treatment of patients with endometrial cancers, there are limited studies evaluating the effects of hormone therapy targeting AR; complicated by the contradictory findings regarding the androgen levels in females." (PMID 37725629, 2023). "Three of these NHRs – progesterone receptor (PGR), estrogen receptor 1 (ESR1), and androgen receptor (AR) – have been previously reported to lose expression in subsets of endometrial carcinomas, which confirms that our approach can capture NHRs known to lose expression in endometrial carcinoma." (PMID 32894083, 2020).
endometrial cancer (continued). "In the present study, we aimed to evaluate the AR expression in endometrial cancers and found that a significant proportion of endometrial cancers especially serous cancers exhibit AR expression, that may have clinical and therapeutic significance." (PMID 29747687, 2018). "18/89 (20.2%) cases of endometrial carcinoma showed positive androgen receptor expression." (PMID 29747687, 2018). "The expression pattern of AR was investigated in relation to aggressiveness of endometrial cancer." (PMID 27384477, 2016). "A large proportion of metastatic endometrial cancer lesions express AR, which may be a potential target in these patients." (PMID 27384477, 2016). "Similar studies in endometrial cancer patients could reveal whether AR could be a potential target also in endometrial cancer patients with high AR to ERα ratio." (PMID 27384477, 2016). "Our preliminary results indicate that enzalutamide may inhibit proliferation in AR positive primary endometrial cancer cells." (PMID 27384477, 2016). "Given the similarities of breast and endometrial cancers, exploring AR expression in endometrial cancer might reveal new therapeutic strategies." (PMID 27384477, 2016). "It is still unsettled if AR could predict outcome and also, whether there is a role for androgen targeting drugs in endometrial cancer treatment." (PMID 27384477, 2016). "Since a large proportion of metastatic endometrial cancers express AR, this may serve as a potential therapeutic target for this patient group, and particularly in the group with a high AR to ERα ratio." (PMID 27384477, 2016). "The androgen receptor (AR) activated by the binding of androgen could enhance the proliferation of endometrial cancer cells by the Notch signaling pathway." (PMID 25866823, 2015). "Sex hormones, through their receptors, such as the androgen receptor (AR) and estrogen receptors (ERα and ERβ), play crucial roles in the development, progression, and treatment resistance of hormone-responsive cancers like prostate, breast, ovarian, and endometrial cancers." (PMID 41155227, 2025). "To determine whether FOXP4 is a downstream target molecule of the androgen/AR pathway in endometrial cancer, we performed a Chip-sequence assay and found that androgen/AR or its transcription complex bound to intron 1 of the hFOXP4 coding region of AR_HEC50B cells." (PMID 38890503, 2024). "Still, the high number of primary tumors and metastatic lesions with intact expression of AR could point to an unexploited potential for treatment targeting AR in endometrial cancer, and it might be of particular interest in specific subgroups as observed for other cancer types." (PMID 27384477, 2016). "One study exploring the role of androgen receptor (AC) in endometrial cancer suggested that KDM4B together with AR can activate the well-recognised oncogene, MYC, by removing H3K9me3 marks in endometrial cancer cells with high basal levels of AR." (PMID 33669182, 2021). "In the context of endometrial cancer, receptLoss correctly identified several well-known nuclear hormone receptors, including ESR1, AR, and PGR, that have previously been shown to have low expression in a subset of endometrial carcinomas." (PMID 32894083, 2020). "AR target genes such as XBP1, MYC, ZBTB16, and UHRF1 were previously reported to be induced by DHT treatment in AR-positive endometrial cancer MFE-296 cells." (PMID 29642629, 2018). "In the endometrial cancer cell, AR-QS but not AR-QL interacts with the anyl hydrocarbon receptor (AhR) bound to benzo [a] pyrene, an environmental factor, and enhances cancer growth." (PMID 38890503, 2024).